MCL1 (MCL1 apoptosis regulator, BCL2 family member)
Diseases named in the same sentence as MCL1 in open-access papers (continued):
Sharing a sentence is not in itself a finding about the gene and the disease.
breast carcinoma (continued). "Using breast cancer cell lines and xenograft models we show that RMC-6272 causes apoptosis specifically in PIK3CA and PTEN mutant ER+/HER2- breast cancer cell lines through suppression of the rapamycin resistant, mTORC1 substrate 4EBP1 and reduction of the pro-survival protein MCL1." (PMID 37264081, 2023). "Finally, to test the hypothesis that high MCL-1 levels in breast cancer cells help those cells escape mitotic cell death, we used siRNA-mediated targeting of MCL-1 in Taxol resistant BT549 cells and study their response to Taxol." (PMID 36672454, 2023). "The objective of the present study was to verify whether the interaction between moxifloxacin (MFLX), one of the fluoroquinolones, and MITF/Mcl-1 protein, could affect the viability, proliferation, and apoptosis in human breast cancer using both in silico and in vitro models." (PMID 36045272, 2022). "This indicates that, in addition to Mcl-1 silencing by siRNA (siMcl-1) in MCF-7 with substantial Mcl-1 reliance, rationally devised combination treatment may cause the death of cancer cells in breast cancer." (PMID 35745769, 2022). "The therapeutic potential of simultaneously blocking BCL-xL and MCL-1 has been reported in many cancers, and we recently demonstrated this strategy in ER + breast cancer using a sequential regime, although BCL-xL induced thrombocytopenia may challenge its clinical implementation." (PMID 35393436, 2022). "Furthermore, the presented results suggest that MITF and Mcl-1 proteins could be considered as the target in the therapy of breast cancer." (PMID 36045272, 2022). "Interestingly, targeted CDK9 inhibitors, such as voruciclib, potently induce apoptosis through MCL-1 depletion in many hematologic cell lines and in a subset of breast cancer cell lines, and have recently entered clinical trials for the treatment of hematological malignancies." (PMID 35349392, 2022). "We, therefore, tested whether the CDK inhibitor, dinaciclib, could block MCL-1 in preclinical HER2-amplified breast cancer models and therefore sensitize these cancers to dual HER2/EGFR inhibitors neratinib and lapatinib, as well as to the novel selective HER2 inhibitor tucatinib." (PMID 33589591, 2021). "It has been recently reported that resistance to MCL-1 treatment in a metastatic model of breast cancer could be mediated by BCL-xL; in fact, we validated this observation performing DBP with the HRK peptide, as we observed a synergistic combination when sequentially combining S63845 and A-133." (PMID 34359829, 2021). "In addition, Myc and MCL1 might cooperatively promote chemotherapy-resistant breast cancer stem cells by regulating mitochondrial oxidative phosphorylation." (PMID 33897436, 2021). "The S1PR1 signaling can regulate the survival of breast cancer cells, which can increase the survival of breast cancer cells by downregulating the pro-apoptotic protein Bim and upregulating the anti-apoptotic protein Mcl-1, respectively, in ERK and PKC-dependent manner." (PMID 33101013, 2020). "Therefore, it could be inferred that the downexpression of Mcl-1 and cyclin D1 was also involved in autophagic cell death in dovitinib-treated breast cancer cells." (PMID 31485222, 2019). "While estrogen receptor (ER)-α+ breast cancers express high levels of three anti-apoptotic Bcl-2 family members (Bcl-2, Bcl-xL, and Mcl-1), pharmacological inhibition of Bcl-2 and/or Bcl-xL fails to induce cell death in ERα+ breast cancer cell lines, due to rapid and robust Mcl-1 upregulation." (PMID 31595181, 2019). "Our evidence suggests that targeting MCL-1 may offer a new therapeutic axis in breast cancer." (PMID 30405205, 2018). "Our previous study showed that MCL-1 could be targeted with miR-26a in breast cancer." (PMID 26036638, 2015).
breast carcinoma (continued). "These preliminary studies suggest that Mcl-1 may support the escape of breast cancer cells from therapy-induced cell death, suggesting that targeting Mcl-1 may be beneficial to improving the outcome of breast cancer patients, particularly those with Mcl-1 amplification." (PMID 25784482, 2015). "Thus, the observations highlighted in this review support a continued effort to design Mcl-1-specific inhibitors, while investigation into the role of Mcl-1 in mammary gland development and breast cancer will be essential to maximize the clinical value of emerging Mcl-1 inhibitors." (PMID 25784482, 2015). "Furthermore, we investigated whether overexpression of miR-193b could increase the DOX sensitivity and determined the potential role of MCL-1 in miR-193b-mediated regulation of DOX resistance in human breast cancer cells." (PMID 26526790, 2015). "Instead, Mcl-1 alone, or in combination with other anti-apoptotic Bcl-2 family members, may be an essential driver of tumor progression and mediator of therapeutic resistance in breast cancers." (PMID 25784482, 2015). "Our previous studies with siRNA delivery were able to sensitize breast cancer cells by targeting anti-apoptotic proteins survivin and Mcl-1, so that this class of proteins (rather than cell cycle proteins) might be more suitable to target for chemo-sensitization." (PMID 25763370, 2015). "Therefore, a better understanding of estrogen-mediated Mcl-1 up-regulation may allow for better targeted therapies for breast cancer patients." (PMID 24971890, 2014). "Several studies on breast cancer have shown that miR-26a can inhibit cell proliferation, colony formation and migration, as well as promote apoptosis by regulating several carcinogenesis-related processes, including several mechanisms that involve the targeting of MCL-1, MTDH and EZH2." (PMID 25184951, 2014). "Thus, one promising approach for the treatment of HER2 overexpressing breast cancers might be one that relies on the use of inhibitors of the anti-apoptotic activity of Mcl-1." (PMID 21899728, 2011). "Herein, for the first time, we have demonstrated that MIM1 – the Mcl-1 protein inhibitor- exerts high cytotoxic and proapoptotic activity towards MDA-MB-231 breast cancer cells." (PMID 40892149, 2025). "Upregulation of anti-apoptotic proteins Bcl-2, Bcl-xl, and Mcl-1 in endocrine therapy-resistant, CDK4/6i-resistant, and HER2 TKI-resistant breast cancer cell lines validates this theory." (PMID 40949156, 2025). "In breast cancer, aggressive B-cell lymphoma and glioblastoma, USP9X alleviates tumor cell survival and confers chemoresistance through YAP1, XIAP or Mcl-1 stabilization." (PMID 40246814, 2025). "MCL-1 phosphorylation by ERK is supported by PIN1 and supports survival of breast cancer cells through stabilisation of MCL-1." (PMID 38434478, 2024). "Targeting MCL1 showed promising results in inhibiting TNBC tumor growth in vivo, presenting a potential avenue for therapy in this challenging breast cancer subtype." (PMID 38762181, 2024). "This conclusion followed the observation that the genetic depletion of Mcl-1 lowered both HER2 and HIF-1α levels, hindering the survival of breast cancer cells." (PMID 38920676, 2024). "The siRNA nioplexes targeted in the Mcl-1 mRNA exhibited cell-growth inhibition in both HER2-positive and HER2-negative breast cancer cells." (PMID 37896184, 2023). "The MCL-1 inhibitor AMG176 has been found to be effective in diverse haematological malignancies and in certain solid tumour derived cell lines, such as breast cancer and non-small cell lung cancer." (PMID 36342579, 2023). "Of note, we used two different breast cancer cell lines MCF7A (ER+/PR+) and BT549 (triple negative), and MCF7A cells that expressed much less MCL-1 protein compared to BT549, were more sensitive to Taxol." (PMID 36672454, 2023). "The suppression of Mcl-1 increases the sensitivity of HER2 inhibitors, such as Lapatinib, in HER2 overexpression breast cancer cells." (PMID 37896184, 2023).
breast carcinoma (continued). "The dual treatment of Mcl-1 nioplexes and TZ significantly decreased cell survival and promoted apoptosis compared to their single treatment in HER2-overexpression breast cancer cells." (PMID 37896184, 2023). "ABGE increased the ROS in ER+ breast cancer cells and activated the JNK signaling pathway, thereby reducing MCL-1 expression." (PMID 37352173, 2023). "The induction of antiapoptotic genes, including B-cell CLL/lymphoma 2 (BCL2), BCL2 related protein A1 (BCL2A1), BCL2 like 1 (BCL2L1), BCL2L2, and myeloid cell leukemia 1 (MCL1), has been observed in multiple cancers, including breast cancer." (PMID 36853387, 2023). "MDM2 ligase, coupled with inhibitors of the targets BCL2L1, BRD4, CDK9, PLK1 and MCL1 in stomach cancer, and MDM2 with PIK3C3 inhibitors in breast cancer seemed to be the best therapeutic construction." (PMID 35249548, 2022). "We also previously showed that in luminal breast cancers, MCL-1 expression in tumor cells, leading to a survival advantage, was extrinsically favored by neighboring CAFs, which themselves exhibit high MCL-1 expression." (PMID 36104324, 2022). "MDM2 ligase coupled with inhibitors of the targets BCL2, BRD4, CDK9, PLK1 and MCL1 in stomach tumor, and MDM2 with PIK3C3 inhibitors in breast cancer, seems to be the best therapeutic strategy." (PMID 35249548, 2022). "The PI3K/Akt and MAPK pathways have been shown to increase the stability of Mcl-1 through the phosphorylation and inactivation of GSK-3β in breast cancer cells." (PMID 35053443, 2022). "Collectively our data demonstrates that combined inhibition of Mcl-1 and AKT/PI3Kβ is effective at killing breast cancer cells resistant to PI3Ki and AKTi in which resistance is caused by sustained mTORC1 signaling." (PMID 36241868, 2022). "MFLX increases Mcl-1 expression and induces apoptosis and DNA fragmentation in MDA-MB-231 breast cancer cells." (PMID 36045272, 2022). "Comparative oncogenomics of these mouse tumors and human breast cancers identifies common amplification of the MCL1 locus, and MCL-1 overexpression was shown to accelerate mammary tumor development in this mouse model." (PMID 35349392, 2022). "HER2-positive breast cancer has significantly lower NOXA levels and mediates resistance to HER2 inhibitors through upregulation of MCL-1." (PMID 33883020, 2021). "We have demonstrated recently that HER2-amplified breast cancers have significantly lower NOXA levels, leading to MCL-1-mediated resistance to HER2 inhibitors through suppression of apoptosis." (PMID 33589591, 2021). "Previous studies have grouped human breast cancer cell lines into MCL-1-dependent and MCL-1-independent groups based on in vitro sensitivity to MCL-1 inhibition or knockdown in 2D monolayer assays." (PMID 33785871, 2021). "Downregulation of MCL1 mRNA levels upon ANO1 knockdown was concordant with a decrease at the protein level, as well as with previous observations in breast cancer cell lines." (PMID 33803266, 2021). "Altogether, these data indicate that dinaciclib downregulates MCL-1 and sensitizes to HER2 inhibitor in HER2-amplified breast cancers." (PMID 33589591, 2021). "We demonstrate here the crucial role of MCL-1 and BCL-xL in ER+ breast cancer, reinforcing the possible therapeutic use of BH3 mimetic combinations for this type of cancer to avoid patient relapse." (PMID 34359829, 2021). "In particular, it has been reported that tamoxifen-treated ER+ breast cancers often present high BCL-2 and BCL-xL expression, and that tumors harboring elevated MCL-1 protein expression exert poorer prognosis." (PMID 34359829, 2021). "High levels of the anti-apoptotic BCL-2 family member MCL-1 are frequently found in breast cancer and, appropriately, BH3-mimetic drugs that specifically target MCL-1’s function in apoptosis are in development as anti-cancer therapy." (PMID 33785871, 2021).
breast carcinoma (continued). "Despite indifference to loss or inhibition of MCL-1 in 2D culture, the impact of targeting MCL-1 in a tumoursphere assay was dramatic that suggests that the biological relevance of targeting MCL-1 in vivo may be underestimated by interpretation of human breast cancer cell line 2D culture." (PMID 33785871, 2021). "In all, we propose that treating HER2-positive breast cancers by co-targeting HER2 and MCL-1 can be achieved with the CDK inhibitor dinaciclib, which is clinically advanced." (PMID 33589591, 2021). "Given the profound requirement for MCL-1 in tumours and cancer stem cells in the mouse MMTV-PyMT model, we wished to interrogate the relevance of these findings to human breast cancer." (PMID 33785871, 2021). "The viability of the breast cancer cell line MCF-7 and MDA-MB-231 upon exposure of siRNA targeting three anti-apoptotic genes, namely, Mcl-1, Bcl-2, and survivin, was examined by MTT assay." (PMID 33919902, 2021). "p-Akt, p65NFκB, p-γH2AX, MCL1, GRP78 and VIM markers were expressed highest in the GFP-positive breast cancers while αSMA was expressed predominantly in the GFP-negative MSCs." (PMID 34239043, 2021). "Nevertheless, the contribution of BCL-2 to MCL-1 inhibition is minor compared to the one observed with BCL-xL, indicating that the anti-apoptotic MCL-1/BCL-xL axis is the predominant one in breast cancer, as previously reported." (PMID 34359829, 2021). "We indeed observed that CAF modulate BCL-2 dependence in luminal breast cancer cells via IL-6 signaling, shifting from a BCL-2 to a MCL-1 survival dependence." (PMID 32722518, 2020). "Recently, VU661013, a new Mcl-1-specific inhibitor, has been reported to rescue venetoclax resistance in AML and inhibit cell survival in estrogen receptor-positive breast cancer when used in combination with navitoclax." (PMID 32455818, 2020). "Additional tumor formation studies in mice confirmed an essential role for MCL-1 in the development of acute myeloid leukemia (AML), T-cell lymphomas and breast cancer." (PMID 33308268, 2020). "The addition of ABT-263 to cultures of breast cancer cells results in a transient apoptosis induction, due to a rapid upregulation of MCL-1 and subsequent sequestration of BIM by MCL-1." (PMID 33308268, 2020). "In breast cancer, SRSF5 is shown to regulate alternative splicing of Mcl-1 pre-mRNA to produce Mcl-1L." (PMID 32106418, 2020). "With the ongoing development of Mcl-1 specific BH3-mimetics, a better understanding of the role of Mcl-1 in breast cancer is imperative." (PMID 31595181, 2019). "Here, we assessed the Mcl-1 inhibitor VU661013 in ER+ breast cancer cells, finding that VU661013 induced caspase activity, inhibited growth, and induced apoptosis of ER+ breast cancer cells in culture and in vivo." (PMID 31595181, 2019). "The results of the research presented herein show that ChPL induces apoptosis in breast cancer cells through MAP kinase signaling inhibition and activation of the mitochondria-mediated pathway involving Mcl-1 downregulation." (PMID 31404252, 2019). "However, the combination of ABT-263 with VU661013 blocked tumor growth, supporting the hypothesis that Mcl-1 targeting improves treatment response of ER+ breast tumors to ABT-263, and highlighting the potential utility of Mcl-1 inhibitors in ER+ breast cancers." (PMID 31595181, 2019). "Consistent with blockade of Mcl-1 activity, treatment of cells for 4 hrs with VU661013 increased Caspase 3/7 activity in ER+ breast cancer cells." (PMID 31595181, 2019). "PLA confirmed increased Mcl-1 activity in ERα+ breast cancer cells treated with ABT-263, while showing that Mcl-1 activity was diminished in cells treated with RAD001, even in those cells treated with ABT-263." (PMID 31595181, 2019). "While ABT-263 induced Mcl-1 protein upregulation in ERα+ breast cancer cells, RAD001 abrogated Mcl-1 induction by ABT-263." (PMID 31595181, 2019).
breast carcinoma (continued). "Of note, we observed that MCL-1–positive breast cancer fibroblasts tended to have an activated morphology, whereas MCL-1–negative CAFs tended to resemble fibrocytes, suggesting a specific role for MCL-1 that needs to be determined." (PMID 30631150, 2019). "Further, we report that the combined inhibition of Mcl-1 using VU661013 with blockade of Bcl-2/Bcl-xL using ABT-263 resulted in superior tumor cell killing and tumor growth inhibition in ERα+ breast cancers in culture and in vivo." (PMID 31595181, 2019). "More than half of the breast cancers with MYC-high status expressed a high level of BCL-2, BCL-XL, or MCL-1." (PMID 30728358, 2019). "In agreement with recent studies, we found that targeting MCL-1 in TN breast cancer cells; in our case using three different BH3-mimetics specific for MCL-1 (UMI-77, S63845 and A1210477); inhibited TN breast cancer cell line growth in vitro." (PMID 29339815, 2018). "Additionally, fulvestrant treatment further increased tumor cell killing induced by MCL1 si-NPs in LTED-selected cells lines, suggesting that Mcl-1 targeting in combination with second-line fulvestrant treatment may be a clinical strategy to increase tumor cell death in ERα+ breast cancer patients." (PMID 29343814, 2018). "Previous reports have shown that bufalin enhanced TRAIL-induced apoptosis in MCF-7 and MDA-MB-231 breast cancer cells by activating the extrinsic apoptotic pathway, the downregulation of Cbl and the inhibition of STAT3/Mcl-1." (PMID 30574018, 2018). "In vitro knockdown of MCL-1 and BCL-XL also enhanced the lethality of lapatinib in breast cancer cells." (PMID 30305055, 2018). "Based on our data we believe that MCL-1 and TRAIL targeted therapies warrant further investigation in patients with treatment refractory HER2-positive breast cancer." (PMID 30305055, 2018). "Maintaining a similar anti-apoptotic effect on MCL1 as it did to BCLx, knockdown of SRSF1 significantly increases the levels of MCL1S isoform in both MCF7 and MDA-MB-231 breast cancer cell lines, and the JAr choriocarcinoma cell line." (PMID 29361709, 2018). "Our results reveal that Mcl-1 and BOK constitute a regulatory feedback loop as ectopic BOK expression induces Mcl-1, whereas silencing of Mcl-1 results in reduced BOK levels in breast cancer cells." (PMID 29156771, 2017). "Nevertheless, depletion of both BOK and Mcl-1 rescued the effect of Mcl-1 silencing on long-term viability of MDA-MB-231, MDA-MB-468 and MCF7 breast cancer cells." (PMID 29156771, 2017). "Our results show that JNK, in fact, negatively regulates Mcl-1 in both T47D and HCC1428 breast cancer cells, and knockdown of JNK1 partially reversed Mcl-1 downregulation caused by S6K2 deficiency." (PMID 28301598, 2017). "Co-transfection of Mcl-1-3’-UTR luciferase construct and miR-296-5p led to significantly reduced levels of luciferase activities compared to mock transfected breast cancer cells." (PMID 29156771, 2017). "Inhibition of STAT3 by both curcumin and its analogue hydrazinocurcumin blocks protein expression of both Mcl-1 and Bcl-2 in MDA-MB-231 and MCF-7 breast cancer cells." (PMID 29262529, 2017). "The effect of metformin treatment on breast cancer cell viability and miR-26a, BCL-2, PTEN, MCL-1, EZH2, and MTDH modulation were evaluated." (PMID 27517917, 2016). "In summary, we show that FBXW7 plays a prominent role in paclitaxel-induced apoptosis by regulating MCL1 and PLK1 levels in breast cancer, as resistant cells loose FBXW7 and accumulate these substrates." (PMID 27409838, 2016). "We investigated the levels of MCL-1 and the other BCL-2 family members BCL-2, MCL-1, BIM, PUMA and NOXA in 32 human breast cancer and immortalized breast epithelial cell lines." (PMID 27931239, 2016). "GSI-I has been reported to induce NOXA expression specifically in melanoma, breast cancer, and multiple myeloma, and one of NOXA's main functions is to bind to and inhibit MCL-1." (PMID 27829238, 2016).